INS (insulin)
Diseases named in the same sentence as INS in open-access papers (continued):
Sharing a sentence is not in itself a finding about the gene and the disease.
type 2 diabetes (continued). "In vivo, the acute first-phase insulin response might be reversed after hyperglycemia is resolved, as T2DM remissions were found initially after bariatric surgery or intensive medication therapy in Remission Evaluation of Metabolic Interventions in Type 2 diabetes (REMIT study)." (PMID 35057503, 2022). "However, in agreement with our results, a single bout of moderate-intensity cycling exercise performed in a large group of 60 patients with type 2 diabetes under strict dietary standardization showed no significant changes in SD, in both non-insulin- and insulin-treated patients." (PMID 35612843, 2022). "Since studies in individuals with type 2 diabetes have shown strong negative correlations between serum Mg2+ and parameters related to insulin sensitivity, we divided the cohort into quartiles based on insulin dose, (determined by the amount of insulin treatment in units per kg body weight)." (PMID 35440685, 2022). "Type 2 diabetes (non-insulin-dependent or T2DM) is a chronic disease characterized by hyperglycaemia resulting from defects in insulin secretion and/or action and increased hepatic glucose output." (PMID 33920838, 2021). "It is therefore likely that discrepant results in earlier type 2 diabetes studies, all of which reported C peptide/DR relationships without insulin measurements, may be due to the complexity of using C peptide as a marker of beta-cell function in the presence of kidney disease." (PMID 34912295, 2021). "With regards to components of oral health, women using OAD and insulin were more likely to report wearing dental prostheses [adjusted OR = 2.05 (95% CI 1.36 to 3.09)] and having loose teeth [adjusted OR = 1.80 (95% CI 1.18 to 2.75)] compared to women without type 2 diabetes." (PMID 34162373, 2021). "The benefits of self-monitoring of blood glucose (SMBG) on glycemic control among type 2 diabetes (T2DM) patients not receiving insulin remains controversial." (PMID 33441946, 2021). "Among adults with type 2 diabetes receiving long-acting insulin with a glycated hemoglobin A1c level of 6.8% to 8.5%, is there a difference in cardiovascular events and mortality among individuals who do or do not initiate additional treatment with short-acting insulin?" (PMID 34559229, 2021). "Furthermore, in a cross-sectional study involving 346 individuals with type 2 diabetes and biopsy-proven NAFLD, multivariate models analysis showed that treatment with insulin (but not metformin) was significantly associated with a higher prevalence of NASH (OR 2.24, p = 0.025) but not fibrosis." (PMID 33877366, 2021). "Obesity and type 2 diabetes mellitus (T2DM) are both combined with decreased FXR activity and impaired metabolism of bile acids, with consequent alteration of hepatic lipid homeostasis and, what is more important, of insulin sensitivity." (PMID 34948230, 2021). "Type 2 diabetes mellitus (T2DM) is characterized by hyperglycemia, insulin resistance, and a relative lack of insulin that mainly occurs in obese subjects and is very common in middle-aged and elderly people." (PMID 34881082, 2021). "Then, we compared the clinical decisions made by the machine learning approach (trained using the database of specialists’ judgments) with those made by nonspecialists regarding whether to prescribe insulin for patients with type 2 diabetes at the first consultation." (PMID 33502325, 2021). "Patients with LADA do not initially require insulin and have the same clinical characteristics as type 2 diabetes mellitus (T2DM) patients at diagnosis." (PMID 34121168, 2021). "Metformin is the established cornerstone of treatment in patients with early (around time of diagnosis) and advanced type 2 diabetes mellitus (T2D), with and without insulin therapy." (PMID 33830998, 2021).
type 2 diabetes (continued). "While direct evidence is lacking, ASP could promote hypothalamic insulin sensitivity leading to increased satiety despite reduced food intake, mechanism demonstrated after central administration of metformin, first-line agent for type 2 diabetes." (PMID 33927690, 2021). "Finally, we could not distinguish between type 1 and type 2 diabetes, including those with insulin use, in the present study." (PMID 31686204, 2020). "However, for the therapy of diabetes mellitus type II in which tissues have lost sensitivity to insulin, a direct induction of glucose uptake with a light-controllable opto-IR1 in major insulin target tissues, such as liver, muscles and adipose tissue, could be required." (PMID 33209247, 2020). "However, impairments in insulin sensitivity are not always observed in normoglycemic offspring with a family history of type 2 diabetes (FH+) compared to those without a family history of type 2 diabetes (FH–)." (PMID 32231642, 2020). "In newly diagnosed type 2 diabetes patients, compared with patients without medications, patients with one oral hypoglycemic agent had higher possibilities of reaching glycemic control, whereas patients using insulin had lower possibilities of reaching the target." (PMID 31161658, 2020). "In patients with type-II diabetes, severe hypoglycaemic events occurred in 5.1% of patients treated with TI, versus 1.7% hypoglycaemic events treated with placebo (Technosphere powder without insulin), and non-severe hypoglycaemia occurred in 67% versus 30%, respectively." (PMID 32785196, 2020). "There is evidence, although not conclusive, that the use of insulin and oral insulin secretagogues, including sulfonylureas, may be associated with an increased risk of HCC in patients with type 2 diabetes possibly through insulin-mediated cancer cell proliferation." (PMID 32518675, 2020). "Here, marked hyperglycemia and markedly impaired insulin secretion without changes in obesity or adiposity were shown in the R2 congenic strain, indicating that a gene located in segment B on Chr 11 promote type 2 diabetes independent of obesity and adiposity under high sucrose environment." (PMID 32703163, 2020). "Moreover, administration of NMN, in a murine model of type 2 diabetes (T2D), restores HFD-induced p65 subunit acetylation of NF-κB and the inflammatory gene response, improving also hepatic insulin sensitivity, via SIRT1 activation." (PMID 32485811, 2020). "However, unbiased lipidomic analysis of skeletal muscle biopsies does not consistently reveal a signature of higher levels of insulin-desensitising bioactive lipids in the muscle of individuals with type 2 diabetes compared with lean sedentary or physically trained individuals." (PMID 32880685, 2020). "Although we did not explore the glucose and insulin response to EAAs in the current study, this could form the basis for future studies to uncover the role of EAAs, especially isoleucine, in the prevention of type 2 diabetes." (PMID 32566281, 2020). "Type 2 diabetes mellitus (T2DM), a common chronic noncommunicable condition in clinic, is featured by physical metabolic disorder and manifested as absolute hyperglycemia and relative insulin insufficiency (caused by inadequate insulin secretion or insulin receptor insensitivity)." (PMID 31977884, 2020). "Interestingly, obese African-American men, but not women, are resistant to the anti-lipolytic action of insulin, which may contribute to the higher prevalence of obesity, and ultimately type 2 diabetes, among African-American women." (PMID 32354182, 2020). "The mechanisms by which PIP4K regulates insulin signalling remain unclear but the use of our assay on human samples of small size and high value could help in the study of the role of this enzyme and its control of PI5P levels in human type II diabetes settings." (PMID 31652444, 2019).
type 2 diabetes (continued). "Type 2 diabetes mellitus (T2DM) is a chronic metabolic–endocrine disorder characterized by hyperglycemia, insulin resistance or relative lack of insulin, and this glucotoxic state promotes tissue oxidative/nitrosative stress and chronic inflammation." (PMID 30866531, 2019). "Additionally, insulin users, whether with type 1 or type 2 diabetes, experienced a greater decrease in HbA1c than noninsulin users, at both 3 months (0.8%; P=.04) and 6 months (1.0%; P=.05)." (PMID 31593545, 2019). "Patients with type 2 diabetes not using insulin had the highest percentage of BG checks within the target range of 70-180mg/dL (89.0%; SD 15.9), compared to participants with type 2 diabetes on insulin (68.1%; SD 28.1) and type 1 diabetes (57.9%; SD 22.5) throughout the 12 months." (PMID 31593545, 2019). "Moreover, insulin mixture therapy was found as an important factor modifying the plasma profile of NGAL, increasing the concentration of this bioactive molecule in the plasma of patients with type 2 diabetes, after 6 months of its use, in relation to the concentration before treatment." (PMID 31195747, 2019). "Interestingly, diminished insulin-stimulated AKT signaling has been documented in the total lymphocytes of obese individuals, and reduced expression of insulin receptor and downstream signaling molecules have also been reported in patients with type 2 diabetes." (PMID 31756626, 2019). "It was reported that the patients with type 2 diabetes mellitus (T2DM) who develop DN have been shown to be more insulin resistant than those who do not." (PMID 29311680, 2018). "Also, as shown for proteins, small pools of compounds can turn over more than 100% per day when utilized at increased rates in persons with type 2 diabetes and this may not be affected by insulin therapy." (PMID 29879181, 2018). "Therefore, insulin therapy in type 1 or type 2 diabetes is not discussed here." (PMID 30541568, 2018). "The authors were in a position to distinguish between type 1 diabetes (“insulin dependent”) and type 2 diabetes, T2DM, (“non-insulin treated” and “insulin-treated non-insulin dependent diabetes”)." (PMID 29386666, 2018). "However, it is possible that the HIC index might be no longer precise method to compare the insulin clearance level in Japanese type 2 diabetes." (PMID 29791512, 2018). "The existing hypothesis “There is not enough insulin” can be activated only for patients with diabetes type 1 and for patients with diabetes type 2 on insulin therapy, while a new hypothesis “medication is not taken” can be created and activated for a patient with type 2 diabetes for example." (PMID 30291097, 2018). "Yet unlike sedentary individuals with comorbid depression and Type-2 diabetes, endurance-trained athletes appear to exhibit a higher mitochondrial density and mitochondrial enzyme capacity, which enhances oxidative phosphorylation and reduces the degree of insulin-sensitizing metabolic byproducts." (PMID 30093853, 2018). "Since inflammation and oxidative stress are associated with the etiology of type 2 diabetes even in non-obese type 2 diabetes and insulin signaling is also interconnected to the JNK signaling pathway, Therefore, various lancemasides in CLW may be effective components for alleviating type 2 diabetes." (PMID 29104217, 2017). "Type 2 diabetes mellitus (T2DM), namely non-insulin-dependent DM or adult-onset diabetes, is characterized by insulin resistance (IR) and relatively insulin secretion reducing." (PMID 28280467, 2017). "Interestingly, in our obese, older and sedentary subjects, there was no increase of JO2 in response to insulin, which appears to be consistent with what has been previously demonstrated in patients with type-2 diabetes when compared with young, healthy individuals." (PMID 29161316, 2017).
type 2 diabetes (continued). "However, we could not document any relation to family history of Type 2 diabetes nor to the post-absorptive phase and, thus, confirm its importance for subsequent degree of insulin release or glucose tolerance." (PMID 28288176, 2017). "In this study, we therefore asked whether common genetic variation [minor allele frequency (MAF) ≥0.05] in the DPP4 gene exists that affects incretin levels, insulin secretion, and glucose tolerance in non-diabetic individuals recruited from the TÜbingen Family study for type 2 diabetes (TÜF)." (PMID 28750074, 2017). "In conclusion, these findings demonstrate GPR142 is a Tryptophan receptor critically required for insulin and incretin hormone regulation and suggest GPR142 agonists may be effective therapies that leverage amino acid sensing pathways for the treatment of type 2 diabetes." (PMID 27322810, 2016). "It is interesting to note that insulin can influence glomerular permeability to albumin in patients with type 2 diabetes but not in healthy subjects, suggesting that disruption of the insulin signaling cascade may be sufficient for insulin to result in microalbuminuria in type 2 diabetes." (PMID 27434075, 2016). "Based on our critical review, we conclude that currently available evidence based on randomized controlled trials and longitudinal studies suggest that vitamin D supplementation might not improve hyperglycemia, beta cell secretion or insulin sensitivity in patients with established type 2 diabetes." (PMID 25722966, 2015). "In type 2 diabetes (T2D), the addition of basal insulin is an option when oral therapy does not maintain acceptable glycaemic control." (PMID 29632572, 2015). "Still, we argue that as groups, those treated with insulin and no oral antidiabetic agents can be considered having type 1 diabetes, whereas those treated with oral antidiabetic agents, irrespective of use of insulin, and those not receiving medication can be assumed to have type 2 diabetes." (PMID 26010615, 2015). "Considering that the PPARG expression regulates lipid and glucose metabolism, insulin action and adipocyte differentiation the effect of cardiorespiratory fitness on PPARG may contribute to the prevention of future metabolic diseases in adults such as type 2 diabetes." (PMID 25879043, 2015). "Interestingly, we found lower mitochondrial staining in myotubes from severely obese with type 2 diabetes compared to cells from severely obese non-diabetic donors, in accordance with earlier studies showing lower mitochondrial content in insulin resistant muscle." (PMID 25790476, 2015). "However as adolescents with Type 2 diabetes also may take insulin, we cannot completely rule out the possibility of misclassification." (PMID 25303963, 2014). "Type 2 diabetes (T2DM) appears when insulin secretion is no longer sufficient to compensate for peripheral insulin resistance." (PMID 25058609, 2014). "Thus, the assigned control group in the present study was clearly insulin resistant similar to the patients with type 2 diabetes but had not developed similar decrease in beta-cell function (as assessed by HOMA2%B), despite fulfilling the ADA criteria for impaired fasting glucose." (PMID 24963292, 2014). "A regulatory mechanism involving a cooperative interaction between insulin and glucagon may have evolved to allow for the induction of FGF21 gene expression during a broad range of stress conditions including starvation and diseases arising from overnutrition (e.g. type 2 diabetes)." (PMID 24733293, 2014). "However, for the third study, only patients with type 2 diabetes who had either not received insulin or had received insulin for <2 months prior to giving their informed consent were allowed to enroll in the study and the study population involved a wider age range (25–82 years)." (PMID 23959960, 2014).
type 2 diabetes (continued). "Thus over time, oxidative fibers may be less viable due to the impairment of the insulin-responsive GLUT4 pathway that occurs in CHC22 mice, resulting in the alteration of fiber type composition we observed, which mimics that reported for type 2 diabetes." (PMID 24204966, 2013). "In patients with type 2 diabetes, splanchnic glucose output did not increase with acute infusion of rhIL-6, while glucose disposal was not impaired, suggesting that IL-6 might have favorable action on insulin action." (PMID 23762871, 2013). "Unlike in type 2 diabetes however, patients with NDM due to KATP channel mutations who are treated with sulphonylurea therapy have near normalization of glycated hemoglobin (HbA1c) without significant hypoglycaemia, suggesting that insulin secretion is well regulated." (PMID 24705260, 2013). "This phenomenon may be explained by the specific nature of the pathophysiological defect in NDM; unlike type 2 diabetes (where multiple factors promote glycaemic dysfunction), other physiological regulators of insulin secretion (glucagon like peptide 1, GLP-1, etc.) function normally." (PMID 24705260, 2013). "In a nonobese animal model of noninsulin-dependent diabetes mellitus, the Goto-Kakizaki (GK) rat, the lysosomal enzyme activities in islet tissue showed an abnormal pattern, and this dysfunction was presumed to convey impairment of glucose-induced insulin release." (PMID 23776622, 2013). "Because IRS1 signaling is essential for glucose homeostasis in liver, and is related with the insulin sensitivity and resistance, it is likely that this SNP may affect the function of DRE, which may impact the expression of IRS1 and contribute to type II diabetes." (PMID 24003029, 2013). "In this study the HF mice with or without exercise were severely insulin resistant, as indicated by their increased levels of fasting insulin and glucose, suggesting that they had developed a metabolic condition resembling metabolic syndrome or type 2 diabetes." (PMID 22682013, 2012). "However, many patients with type 2 diabetes do not maintain the recommended glycemic targets over time with traditional therapies and must transition to combination therapy and/or increasing doses of insulin as their glycemic control deteriorates." (PMID 21529363, 2011). "This study was undertaken to assess whether postprandial use of insulin glulisine would be non-inferior to preprandial use in glycaemic control with particular attention to weight changes in patients with type 2 diabetes suboptimally controlled with oral antihyperglycaemic agents and insulin." (PMID 21812890, 2011). "However, it is unclear whether incretin-based drugs are still effective in patients without the capacity for endogenous insulin secretion (that is, no residual β-cell functions; for example, advanced type 2 diabetes or type 1 diabetes)." (PMID 21443773, 2011). "However, neither mice administered long acting analogs of GIP1–42 nor GIP-overexpressing transgenic mice exhibit increases in body weight, food intake, adiposity or insulin resistance, questioning whether GIPR agonists would promote obesity in patients with type 2 diabetes." (PMID 20231880, 2010). "Since it is highly plausible that type 2 diabetes candidate SNPs affect adiposity, insulin sensitivity, or insulin secretion, our negative findings could point to the possibility that these SNPs' associations with type 2 diabetes in part reflect statistical type 1 errors." (PMID 18714373, 2008). "With regard to the relationship between exogenous insulin and adiponectin in vivo, there is one study in pediatric type 1 diabetes reporting an increase in adiponectin 1 month after initiation of insulin therapy, while, to date, there is no published study in type 2 diabetes." (PMID 18507868, 2008).